MALAT1 (metastasis associated lung adenocarcinoma transcript 1)
Diseases named in the same sentence as MALAT1 in open-access papers (continued):
Sharing a sentence is not in itself a finding about the gene and the disease.
cancer (continued). "In particular, in NSCLC, MALAT1 is involved in STAT3, SRSF7, and PBOV1 (prostate and breast cancer overexpressed 1) pathways; MALAT1 affects the levels of miR-124, miR-374b-5p, and miR-28-5p, which in turn, target STAT3, SRSF7, and PBOV1 mRNAs, respectively." (PMID 35630580, 2022). "Finally, six lncRNAs (DLEU2, HOTTIP, MALAT1, NEAT1, SNHG1, and TUG1), registered in Lnc2Cancer 2.0, a database offering comprehensive experimentally supported associations between lncRNA and human cancer, were selected as candidate lncRNAs for the diagnosis of HCC." (PMID 34185961, 2021). "Aberrant expression of MALAT1 and NEAT1 were reported in several types of cancer as hepatocellular carcinoma, pancreatic cancer, ovarian cancer, and colorectal cancer." (PMID 33670447, 2021). "The lncRNAs HOTAIR, MALAT1 and MEG3 were also enriched in EVs derived from cervical-vaginal lavages and significantly upregulated in CC patients compared with cancer-free volunteers." (PMID 34552067, 2021). "A multitude of lncRNAs, such as HOTAIR, H19, MALAT1, MEG3, LET and PVT1, are correlated with cancer development." (PMID 34552067, 2021). "In gastric cancer, it has been demonstrated that MALAT1 can enhance SOX2 mRNA stability, thus promoting stemness in cancer cells." (PMID 34204445, 2021). "Because MALAT1 showed a prognostic value in CRC, and it was a well-studied lncRNA in cancers, we selected ERCC4, miR-200c-3p and MALAT1 for verification." (PMID 34993023, 2021). "A large number of recent studies have focused on exploring the role of m6A-methylated mRNA in cancer cells, and some LncRNAs such as LINC00958, DANCR, and MALAT1 modified by m6A have also been reported." (PMID 34544449, 2021). "Moreover, it has been revealed that MALAT1 could induce MAPK/ERK pathway in some cancer cells." (PMID 35178360, 2021). "Aberrant expression patterns for H19, MALAT1, TP73, ZEB1-AS1, SNHG15, and others were detected in a multitude of other cancer types, as well as in relation to other molecules belonging to the microRNA-200 family." (PMID 35011635, 2021). "In tumor xenograft models, nano complexes of si-MALAT1 targeting cancer stem cells TMZ sensitivity and survival in addition to proliferation inhibition, while MALAT1 overexpression induced TMZ resistance." (PMID 34322395, 2021). "Resveratrol belongs to a group of natural polyphenol compounds called stilbenes, which regulate the expression of lncRNAs-PCAT29, NEAT1, MALAT1, and AK001796 and plays an essential role in cancer inhibition." (PMID 33805687, 2021). "Consistent with other similar studies that reported MALAT1 and PVT1 were correlated with CRC nodal and/or distant metastases and different types of cancer." (PMID 34200314, 2021). "The highly conserved and widespread expression of MALAT1 in mammalian tissues and cancers implies its functional importance; MALAT-1 dysregulation in a variety of cancers has been extensively studied." (PMID 34899344, 2021). "In the following sections, we will review and highlight the characteristics and functions of some of the lncRNAs, i.e., HOTAIR, NEAT1, H19, MALAT1, and MEG3, frequently involved in several female-oriented cancers." (PMID 34885213, 2021). "Various lncRNAs, such as MALAT-1, ATB, and HOTAIR, mediate the EMT of cancer cells through various mechanisms." (PMID 33664479, 2021). "A growing number of lncRNAs, such as MALAT1, NEAT1, and NKILA, have been shown to function as either tumor suppressors or oncogenes in various cancer types." (PMID 33869020, 2021). "In one study, MALAT1 was called noncoding nuclear-enriched abundant transcript 2 (NEAT2), indicating its nuclear abundance in several cancer cell lines, and its role in alternative splicing regulation." (PMID 34012919, 2021). "High levels of transcripts of long non-coding lncRNAs, MALAT1 and NEAT1 (located on the long arm of chromosome 11) have been described in various cancer types including pancreatic cancer." (PMID 32493953, 2020).
cancer (continued). "Importantly, however, both MIR122 and MALAT1 indel mutations could not be confirmed as driver-mutations, and their roles in cancer thus remain unclear." (PMID 33329688, 2020). "For LSCC prognostic lncRNAs, H19, MALAT1, NEAT1, CYTOR and SNHG12 were ranked as the first five of this directly-related-to-cancer list." (PMID 32024523, 2020). "Oncogenic lncRNAs in human cancer, including HOTAIR, MALAT1, PCA3, CASC15, and CASC20 are also annotated in dogs." (PMID 33194754, 2020). "MALAT1 binds miR145-5p and decreases its expression, resulting in increased NEDD9 expression, as miR145-5p targets NEDD9 mRNA 3'-UTR, and cancer cell migration and invasion." (PMID 32174966, 2020). "Metastasis associated lung adenocarcinoma transcript 1 (MALAT1), also known as nuclear-enriched abundant transcript 2 (NEAT2), is a highly conserved and lncRNA of ~ 8 kb in size which is ubiquitously expressed in cancer and normal tissues." (PMID 32209098, 2020). "An example is the documented fusion of MALAT1 to GLI1, which enhances GLI1 expression, and thus hedgehog signaling in different types of cancer." (PMID 33329688, 2020). "In CRC, inhibition of MALAT1 suppresses CRC progression and metastasis and improves the sensitivity of cancer cells to 5-FU." (PMID 32209115, 2020). "Scholars have reported numerous lncRNAs involved in regulating human cancer cell growth and metastasis through the modulation of the RhoA pathway, including SNHG5, LOC554202, and MALAT1." (PMID 33126743, 2020). "Here, we made a comprehensive search using the public database miRcode and Starbase, and miR‐22‐3p was identified to be a target gene of MALAT1, as well as an upstream gene of XIAP in cancer." (PMID 33135336, 2020). "Several other lncRNAs, such as MALAT1 and HOTAIR, also participated in diverse pathways in different cancer types." (PMID 32393270, 2020). "By knocking down or overexpressing MALAT1, we identified its role in promoting the migratory and proliferative capacity of HCC cells, highlighting its status as an oncogene in this form of cancer." (PMID 31777593, 2019). "Similar to MALAT1, NEAT1 is also reported to be a transcriptional regulator of various genes involved in cancer progression." (PMID 30512195, 2019). "Pseudouridylation has also been found in lncRNAs correlated with cancer, such as XIST and MALAT1, as previously discussed." (PMID 30654440, 2019). "In certain cancer types, a MALAT1–NF-κB axis is involved in chemoresistance and EMT, and PI3K-AKT signaling has been found to mediate the effect of MALAT1 on metastasis." (PMID 30781877, 2019). "The results confirmed that the cancer prevention effects triggered by restored ABI3BP and depleted MALAT1 as evidenced by suppressed cell growth and enhanced cell senescence." (PMID 31174563, 2019). "The LncRNA 657 was demonstrated to suppress HCC cell growth by sponging miR-106a-5p and MALAT1 promotes HCC progression by down-regulating miR-146b-5p through its sponge function, thereby promoting cancer growth and metastasis." (PMID 30416681, 2018). "Meanwhile, we focused on the regulative effect of MALAT1 working on HDAC4—a proliferation and apoptosis‐related factor in manifold cancers." (PMID 30094957, 2018). "In esophageal cancer, lncRNAs MALAT1, HOTAIR, AFAP1-AS1, HNF1A-AS1, and CCAT1 are upregulated and promote cancer metastasis through multiple mechanisms, including miRNA sponging, epigenetic modification, and transcription regulation." (PMID 29511340, 2018).
cancer (continued). "LINC01614, CTD-2547G23.4, LINC01355, MALAT1, CTD-2349P21.9 and RP11-468E2.10 were over-expressed, whereas RP11-672A2.4 was under-expressed in cancers." (PMID 29303984, 2018). "Several researches have showed that the increased expression of 6 lncRNAs (H19, UCA1, TUG1, MALAT1, SPRY4-IT1, and HOTAIR) was correlated to poor prognostic outcome of cancers, those findings in consist with our results." (PMID 29870555, 2018). "As in other cancer types, MALAT1 was found to interact with the methyltransferase EZH2 also in MM cells, and both MALAT1 and EZH2 inhibitors reduced H3K27Me3 at KEAP1 promoter, thus upregulating KEAP1 mRNA." (PMID 29487387, 2018). "MALAT1, which is also known as PRO2853, HCN, NCRNA00047, and NEAT2, is one of the first lncRNAs described to play a significant role in cancer metastasis." (PMID 30285605, 2018). "In renal cancer, reciprocal crosstalk among MALAT1, miR205, and EZH2 suppresses the expression of E-Cadherin and enhances Wnt signaling to promote cancer metastasis." (PMID 28671581, 2017). "Several lines of studies, meanwhile, have revealed that a lot of lncRNAs play a important role in cancer prognosis, such as TUG1, SPRY4, MALAT1." (PMID 29163187, 2017). "In OS, MALAT1 promotes proliferation and metastasis of cancer cells by activating the PI3K/Akt pathway; additionally, elevated tissue levels of MALAT1 correlated with advanced clinical stage and distant metastasis, contributing to a shorter survival time." (PMID 29246026, 2017). "The results showed that MAlAT1 and BANCR had similar trend of expression between the two kinds of cancers." (PMID 28938549, 2017). "For example, MALAT1, HOTAIR and NORAD in cancer cells can elicit effective cancer inhibitory effect." (PMID 29220444, 2017). "The objectives of this study were to develop a novel lncRNA MALAT1 near-infrared optical probe, to evaluate the characteristics of this optical imaging probe in vitro and to determine whether it can be used for imaging MALAT1 expression in malignant tumours in vivo." (PMID 29156758, 2017). "The lncRNAs such as MALAT1, GAS5, ANRIL, PVT1, CCAT2 and HOTAIR etc. were found to be novel promising biomarkers to predict a poor prognosis in human cancers." (PMID 28594897, 2017). "Circulating noncoding RNAs such as miR-21, MALAT-1, HOTAIR have been used as biomarkers for cancer diagnosis." (PMID 29137379, 2017). "Knockdown of MALAT1 expression inhibited PC cell proliferation, migration, and invasion in vitro by inducing G2/M cell cycle arrest, suppressing EMT and decreasing cancer stem-like properties." (PMID 29221115, 2017). "This projects MALAT1 as a mediator of KDM5B oncogenic potential and highlights the critical role of this microRNA, lncRNA and histone demethylase in cancer cell motility and metastatic colonization." (PMID 26917489, 2016). "Therefore, MALAT-1 may serve as a biomarker, but its value differs in various cancers." (PMID 27608009, 2016). "Among the well documented lncRNAs involved in cancer migration and metastasis are HOTAIR and MALAT1." (PMID 26871474, 2016). "Circulating lncRNAs as biomarker for cancer diagnosis have been the subject of extensive research for years, such as POU3F3, HOTAIR, H19, MALAT-1, and so on." (PMID 27888803, 2016). "In renal cancer, reciprocal crosstalk among MALAT1, miR-205, and EZH2 suppresses the expression of E-cadherin and enhances Wnt signaling activity, thereby promoting cancer metastasis." (PMID 26989421, 2016). "We compared the mRNA expression level of MALAT1 and Ezh2 in ESCC cancer tissues and found that there was remarkably positive correlation between MALAT1 and Ezh2 expression (P<0.0001)." (PMID 27015363, 2016). "All these results show a possible means as to how MALAT1 induces carcinogenesis by facilitating EMT, cancer progression and metastasis." (PMID 27092491, 2016). "The total fraction lncRNA-derived reads varied between cancers (P<1e-99, one-way ANOVA), to a large extent explained by abundant MALAT1 or NEAT1 in some types." (PMID 28959951, 2016).
cancer (continued). "In this study, we have found MALAT1 exist highest fold change (Tumor/Normal) in KIRC among Pan-Cancer Networks by mining clinical and expression profiles of 14 cancer types (>6000 samples) from TCGA Data Portal." (PMID 26461224, 2015). "In summary, we demonstrated MALAT1 as an important oncogene like other lncRNAs in OSCC and its expression frequently is upregulated in human tumor samples and cancer cell lines." (PMID 26522444, 2015). "The results from tissues showed that MALAT1 was up-regulated in 46.3% (25/54) of ESCC tissues (cancer/normal ratio > 1.5), with the mean expression level of 4.53 in tumors and 3.02 in their counterparts (p = 0.02)." (PMID 25613496, 2015). "The list of lncRNAs which are proposed as biomarkers for cancer diagnosis and prognosis is very long and includes some very well characterized lncRNAs such as HOTAIR, MALAT1, HULC and ANRIL." (PMID 26087192, 2015). "In two cancer cell lines, HeLa and MCF-7, the difference between the exosome and donor cell content of six lncRNAs (MALAT1, HOTAIR, lincRNA-p21, GAS5, TUG1, and CCND1-ncRNA) was assessed in donor cells under DNA damage stress." (PMID 26582468, 2015). "Several of the detected differentially expressed lncRNAs were well described members of cancer-related pathways, including tumor suppressors and oncogenes (e.g. MEG3, Xist, MALAT1, H19, GAS5, and HOTAIR)." (PMID 25264628, 2014). "LincRNAs are gaining increasing importance both as biomarkers in cancer (HOTAIR: breast, liver, pancreas; MALAT-1: NSCLC; PCAT-1: prostate), and as regulators of complex and diverse biological functions." (PMID 24393131, 2014). "A total of 9 CARs overlapped with annotated lncRNAs, of which NEAT1, MALAT1, and MEG3 are known to be regulated by cancer pathways." (PMID 25264628, 2014). "The expression of MALAT1 was measured in the cellular fraction of peripheral human blood and the expression levels of NSCLC patients and cancer-free controls of the general population were compared." (PMID 24313945, 2013). "The identification of many well-defined cancer gene markers (representing oncogenes), such as EGFR, osteopontin (SPP1), ERBB3, MALAT1, S100A2, S100A6, ABCC3 and ELN3, as highly discriminative genes by the ECD is quite encouraging." (PMID 22369099, 2011). "MALAT1 and NEAT1 regulate various cellular processes, the inflammatory response, and resistance to anti-cancer treatments; however, their impact on the portability of post-RT adverse effects remains unknown." (PMID 40150019, 2025). "In particular, regarding TC, THER-saturated expression of the lncRNAs MALAT1 and ACVR2B-AS1 enhanced proliferation, migration, and invasion of cancer cells, by acting as microRNA sponges that would upregulate oncogenic targets and pathways, with TERT’s direct involvement still obscured." (PMID 41154428, 2025). "E-cadherin and vimentin (EMT markers): MALAT1 expression demonstrated a negative correlation with E-cadherin and a positive correlation with vimentin (p < 0.001), consistent across all cancer types." (PMID 40674376, 2025). "Similarly, HPV-related cancers exhibit EV-carried oncogenic lncRNAs (HOTAIR, MALAT1) in cervicovaginal fluid for early malignancy detection, and SARS-CoV-2 utilizes platelet-derived EV counts and lipid profiles (GM3) to gauge disease severity." (PMID 40809518, 2025). "Although direct correlation between plasma and matched tumor expression levels of SOX2, PIWI proteins, and MALAT1 was not assessed in this study, prior research supports their concordance in several cancers." (PMID 40674376, 2025). "Specifically, mutant MALAT1 lacking m6A‐motifs suppresses the metastatic potential of cancer cells, both in vitro and in vivo." (PMID 40783798, 2025).
cancer (continued). "This comprehensive analysis identified a batch of core lncRNAs that exhibited strong associations and high regulatory potential across multiple cancers, including NEAT1, MALAT1, GAS5, TP53TG1, and LINC00941, many of which have been previously confirmed to be closely related to cancer progression." (PMID 41373831, 2025). "LncRNAs such as MIAT, SNHH16, LUCAT1, OIP-AS1, MALAT-1, GAS5, and H19, which regulate functions that might disrupt different steps of the cancer–immunity cycle, have been found in EVs." (PMID 40429961, 2025). "In a notable preclinical study, targeting the MALAT1 ENE (Exonuclease Protection Element) triplex with small molecules holds great promise for developing novel anticancer therapies and molecular tools to investigate MALAT1-driven cancers." (PMID 39015773, 2024). "Despite its prominent role in cancer, MALAT1 remains not solely found in cancerous cells and exhibits widespread expression across various tissues and cell types." (PMID 39323624, 2024). "In addition, MALAT1 has also been found to regulate various signaling pathways, including NF-KB, Wnt/β-catenin, Notch, and PI3K/AKT/mTOR, contributing to cancer development." (PMID 39502508, 2024). "AA patients had elevated plasma levels of MALAT1 and PVT1 compared with cancer-free smokers." (PMID 38791954, 2024). "The high clonogenic activity of HAN-1 cells can be related to increased expression of several long non-coding RNAs, such as TUG1, MEG3, MALAT1, NEAT1, and DANCR – all considered as modulators of stemness of cancer cells, their differentiation potential and chemoresistance." (PMID 38342891, 2024). "In addition, the natural polyphenolic phytoalexin drug Resveratrol and its derivatives (3,5,4′-trimethoxystilbene and triacetyl Resveratrol) were shown to inhibit the expression of MALAT-1 and the EMT process in several cancers." (PMID 38201661, 2024). "MALAT1 has been identified to bind with Enhancer of zeste homolog 2 (EZH2) and control the downstream genes expression through modifying histone methylation in cancer cells." (PMID 39681821, 2024). "As MALAT1, HOTAIR, and H19 have proven to have roles in cancer progression by regulating proliferation, apoptosis, cell cycle progression, and ROS levels as the main biological functions, these lncRNAs are considered proper targets in the treatment of various malignancies, including AML." (PMID 38777995, 2024). "To test the hypothesis that a cancer-type-specific MALAT1/NR4A1 axis modulates the expression of NR4A1, we evaluated the effect of this axis in specific cancer cell types." (PMID 38791553, 2024). "In addition, MALAT-1 competes with a wide range of different miRNAs and interferes with transcription factors that drive the EMT process, leading to increased cancer invasiveness and chemoresistance." (PMID 38201661, 2024). "LncRNA MALAT1 has not been extensively investigated in mature B-cell malignancies, as opposed to other cancers." (PMID 38255996, 2024). "On the other hand, DANCR, GAS5, MALAT1, and UCA1 are examples of lncRNAs that could potentially inhibit cancer." (PMID 39512820, 2024). "They discovered the function of MALAT-1 in increasing the migration and proliferation potential of HCC cells by knockdown or overexpression experiments and demonstrated its oncogenic property in this type of cancer." (PMID 38511067, 2024). "MALAT1 and HOTAIR showed significant fluctuation in their expression under various cancer types, influencing inflammation, autophagy, migration, metastasis and therapeutic sensitisation, highlighting their potential for acting as a biomarker and therapeutic candidate." (PMID 40176927, 2024). "Furthermore, pre-clinical studies have already demonstrated therapeutic targeting of lncRNAs, such as MALAT1 and HOXB-AS3 in cancer, suggesting their potential clinical value in cancer diagnosis and treatment." (PMID 38516191, 2024).